CD4 (CD4 molecule)
Diseases named in the same sentence as CD4 in open-access papers (continued):
Sharing a sentence is not in itself a finding about the gene and the disease.
cancer (continued). "Previous studies have reported that CD4 + T and CD8 + T lymphocytes recognize cancer antigens and can be incorporated into immunotherapy against cancer." (PMID 32235004, 2020). "CD4+CD25+ FOXP3+Helios+, CD4+CD25-FOXP3+Helios+and CD25+FOXP3+CD73+CD39+Tregs wereexpanded after co-culturing of T cells with both cancer-ASCs and normal-ASCs, while they were statistically significantonly in the presence of cancer-ASCs (P<0.05)." (PMID 31721539, 2020). "We had previously reported that depletion studies in immunocompetent mice treated with IL2-F8-TNFmut revealed a prominent role of CD4+ and CD8+ T cells in the cancer remission process." (PMID 31799191, 2019). "We also inferred that AXIN2 probably regulates the cell differentiation of T cells CD8 and T cells CD4 memory resting through the WNT pathway, subsequently influencing cancer prognoses." (PMID 31681739, 2019). "CD4+ helper T cells and CD8+ cytotoxic T cells (CTL) provide one of the main defenses against cancer cells: they detect and kill cancer cells in their role as managers of humoral and cell-mediated responses." (PMID 30999681, 2019). "In their study, the proportion of naïve, memory, and effector CD4+ and CD8+ cells was similar in the BALF from lung affected by cancer when compared with the contralateral lung." (PMID 31010080, 2019). "Differentiation of IFN-γ-producing CD4 and CD8 T cells, called helper T 1 (Th1) and cytotoxic T 1 (Tc1) cells, is desirable in the development of vaccines and immunotherapies against cancer and infectious diseases." (PMID 30669428, 2019). "This prospective study revealed that baseline CTCs and the cCSC ratio (i.e., cancer status), as well as the CD8+ proportion and the CD4: CD8 ratio (i.e., host immune status), were significantly associated with the prognosis of HNSCC." (PMID 30991692, 2019). "Thus, in both HIV and cancer, loss of target recognition by CAR T cells via antigen escape is an issue, but through simultaneous targeting of multiple antigens or the targeting of biologically important functions such as HIV binding to CD4, this issue seems to be solvable." (PMID 31611880, 2019). "IFN-γ is secreted from many cells, including natural killer (NK) cells, naïve CD4 T cells and CD8+ cytotoxic T cells, and it activates antigen production to eliminate cancer cells." (PMID 30640711, 2019). "In very advanced cancer patients, LDMC downregulated CD4+CD25+ regulatory T cells and at the same time restored the functionality of T and NK cells." (PMID 31683667, 2019). "Next, the expression of hOX40 and mCTLA-4 was assessed on Tregs (CD4+ CD25+ Foxp3+) and conventional T cells (CD4+ CD25− Foxp3−) from tumors of mice with MC38 cancer." (PMID 30975201, 2019). "CD4+ and CD8+ T cells were purified from peripheral bloods and cancer specimens, and were stimulated with low (10 ng/ml) and high (100 ng/ml) concentration of recombinant IL-24." (PMID 31921658, 2019). "Other than fibroblasts, various cells (CD4, CD8 lymphocytes, macrophages, dendritic cells, endothelial cells, pericytes, etc.)and their crosstalk influence remnant cancer cells and sensitivity for chemotherapy." (PMID 31491010, 2019). "It is noteworthy that 19305DP-TCR-transduced CD4+ T cells recognize cancer cells in an MHC class I-restricted manner, in contrast to MHC class II-restriction of conventional CD4+ T cells." (PMID 30626427, 2019). "An increase in immune cells with negative immune regulatory functions, including Tregs, myeloid-derived suppressor cells, and CD4+NKG2D+ T cells, has been demonstrated in cancer patients." (PMID 31511630, 2019). "The function of these Treg cells has been described to suppress proliferation, induction/activation of CD8+ and CD4+ T cells in a COX-2-dependent manner, which is involved in establishing immunological tolerance in cancer immunosuppression." (PMID 30936882, 2019).
cancer (continued). "In the context of cancer, there are two antagonistic classes of T cells that have important roles in the fight against cancer — cytotoxic CD8+ T cells and CD4+ regulatory T cells (i.e. Tregs)." (PMID 30917934, 2019). "CD4+ T helper cells have indeed been shown to be a critical element in optimal activation of CD8+ T cells and in the maintenance of cancer-related immune memory." (PMID 30670061, 2019). "Given their ability to enhance CD4+ and CD8+ T cell responses, opt-36γt and opt-36βt look especially promising for disease models in which cellular responses are important, such as cancer where driving CD8+ immunity is important to clear tumors." (PMID 31121939, 2019). "With regard to the density of immune cells around cancer cells on c-TMA cores, we noted a considerable variation from low density (“cold”) to high density (“hot”) for CD3, CD4, CD8, CD20, CD68, and MPO positive cells." (PMID 31817531, 2019). "CD27 agonism was shown to recapitulate CD4+ T cell help by improving induction of effector CD8+ T cells, antigen-specific cell killing, and overall survival in a murine cancer vaccine model." (PMID 31552045, 2019). "The results indicate that CTCs and cCSCs were independent predictors of cancer progression and OS and that patients with a high baseline CD8+ proportion had longer OS, while patients with a lower CD4: CD8 ratio had longer PFS." (PMID 30991692, 2019). "In this study, we examined the phenotype and function of Treg cells as well as CD4+ and CD8+ Tconv cells that infiltrated into the TME, including the ME and TM from patients with cancer." (PMID 31801611, 2019). "We found that CD31 high expressing tumors had higher fractions of anti-cancer T cells, including CD8+ T cells (p = 0.027), activated memory CD4+ T cells (p = 0.038) and Gamma delta T cells (p < 0.001)." (PMID 30718678, 2019). "The analysis revealed that the proportion of both CD4+ and CD8+CD45RChigh T cells were predictive of cancer, with an AUC of 0.711 ([0.596–0.774], p = 0.002) and of 0.676 ([0.554–0.799], p = 0.01), respectively." (PMID 30925186, 2019). "Of note, whereas significantly higher frequencies of central memory CD4+ and CD8+ T cells were found in cancer tissue relative to adjacent and normal lung tissue, this was not the case for DNT cells." (PMID 30857561, 2019). "We next used ROC curve to study the predicting value of CD4+ and CD8+CD45RC cell frequencies for cancer and to determine the best cut-off values for cancer prediction." (PMID 30925186, 2019). "The CD3+/CD4–/CD8– T-cell percentage might be valuable to use as a generic marker for intracellular infections when investigating fever of unknown origin, although specificity might not be adequate because these percentages can also be elevated in association with some cancers." (PMID 31538915, 2019). "Take cancer type – CESC and gene – CD27, for example, the Cox proportional hazard model is given as follows: Surv(CESC) ~ Purity + B_cell + CD8+T-cell + CD4+T-cell + Macrophage + Neutrophil + Dendritic + NK_cell + mast_cell + CD27." (PMID 31358815, 2019). "FSD13 had a greater ability than wild-type IL-2 in stimulating CD4+ T, CD8+ T, and NK cell proliferation, enhancing the expression of CD69, CD183, CD44, and CD54 in these cells, and triggering cancer cell apoptosis." (PMID 30250191, 2018). "Our studies extend the current understanding about a distinct coinhibitory molecule expression pattern in CD4+ and CD8+ T cells, by showing distinct changes of BTLA and HVEM expressions on CD4+ and CD8+ T cell subset in human cancers." (PMID 30116751, 2018). "Strong ex vivo responses against arginase peptide were detected in IFNγ ELISPOT and arginase-1 specific CD4+ and CD8+ memory T cells were found in both healthy donors and cancer patients." (PMID 30400835, 2018).
cancer (continued). "The CD4-positive T cells augment the immune response against cancers, and CD8-positive cytotoxic T lymphocytes (CTL) directly kill the cancer cells through the degranulation of granzyme, granulysin, or perforin." (PMID 30662919, 2018). "It is well documented that the reduction of CD4+ and CD8+ populations occurred in the peripheral blood of patients suffering from different cancers." (PMID 30079021, 2018). "CD4+ T helper (Th) cells provide cytokine support for CD8+ T-cell proliferation and expansion to eliminate cancer cells and trigger antitumoral responses." (PMID 30042343, 2018). "In contrast to what was seen for CD4+ cells, expression of IFN-γ by CD8+ cells was unaffected by the development of lesions or their progression to cancer." (PMID 29664967, 2018). "The level of local infiltration of CD4+ and CD8+ T lymphocytes has been reported as a good prognostic factor in several cancers, including biliary tract cancer." (PMID 29732001, 2018). "Anti-CTLA-4 mAbs have been extensively studied in mouse models of cancer, where rejection of established tumors relies upon the impact of anti-CTLA-4 on CD4+ and CD8+ Teff and on CD4+FoxP3+ Treg cells." (PMID 29576375, 2018). "Here, we showed that pIL-12 GET is a strong immunostimulatory therapy which generally induced CD4+ and CD8+ T cells expansion for cancer." (PMID 30544810, 2018). "Orchestrating immune responses by CD4 and CD8 T cells was unraveled by a study carried out by the group of Hans Schreiber, interrogating the cooperation of CD4 and CD8 T cell responses in a model of bystander killing of cancer." (PMID 29032503, 2018). "Infiltration of CD4+ and CD8+ cells was significant in the fibrosis near the residual cancer cells and it became obscure as the areas receded from the cancer cells." (PMID 29801474, 2018). "CD4 and CD8 T-cells play critical roles in immunosurveillance against cancer while mDCs confer an increase in immune activation by antigen presentation and activation of those T-cells." (PMID 29440769, 2018). "Median time from CD4, CD4:CD8, CD8, and WBC nadir to cancer diagnosis ranged from 7.25 to 9.75 years." (PMID 30315476, 2018). "In this scenario, CD4 and CD8 T cell responses are part of the cancer immune cycle and both populations significantly influence the clinical outcome." (PMID 29032503, 2018). "Peptide-based vaccines for cancer have many advantages however, for optimization these immunogens should incorporate peptide epitopes that induce CD8, as well as CD4 responses, antibody and long term immunity." (PMID 30200528, 2018). "The complex interaction between the CD4+ TH cells and CD8+ TC cells and other cell types in the TME impacts the outcome of cancer progression and metastasis." (PMID 30237863, 2018). "CD4+ and CD8+ T-lymphocytes are two types of TILs which recognize cancer antigens and inhibit cancer proliferation." (PMID 29996539, 2018). "PSP significantly increased the percentage of CD4+ T lymphocytes, the ratio of CD4+/CD8+/CD14+/CD16_ and the quantity and percentage of the B lymphocytes and finally enhanced the immune system of cancer patients." (PMID 28178285, 2017). "Then, we analyzed the correlation between the Tim-3+ PD-1+ CD4+/CD8+ T-cells and serum concentration of cancer biomarker which was tested pre-treatment." (PMID 29213216, 2017). "Due to its capacity to regulate both CD4+ and CD8+ T cells, OX40 is a promising candidate in immunotherapy of chronic viral infections and cancer." (PMID 28265272, 2017). "While the CD4+Tcc had a similar distribution in the three different sites, CD8+ Tcc were notably numerous on cancer tissue than HM." (PMID 29375559, 2017). "Previous studies have shown that the expression of PD-L1 in TIICs was positively correlated with the number of CD4+ T lymphocytes and CD8+ T lymphocytes, and a high level of expression of CD4+ and CD8+ T cells has been correlated with better cancer survival." (PMID 28969052, 2017).
cancer (continued). "The number of CD95-negative cells was diminished within both CD4+ and CD8+ T cell populations of cancer patients, but in the case of CD8+ cells this reduction was more significant (p = 0.01, data not shown)." (PMID 29075318, 2017). "To compare cancer immune surveillance (represented by TILs: CD8+, CD4+, FOXP3+, CD56+, TAMs: CD68+ and GZB+ cells) in p16Ink4a -positive and negative primary tumors we analyzed mononuclear infiltrates within cancer nests only." (PMID 28515351, 2017). "As additional confirmation of the immune modulating role of cancer cells, in the peripheral blood of CRC patients, we found the presence of CD4+ Tnull cells, whose percentage was significantly higher than that in healthy controls." (PMID 29375559, 2017). "The immune cell infiltration into the cancer tissue included increased numbers of macrophages (CD68+), helper T cells (CD4+), and CD25+ lymphocytes compared to benign tissue." (PMID 28794686, 2017). "The modulation of CD4+ and CD8+ T cells after splenectomy plays a critical role in the immune response against cancer for." (PMID 28549349, 2017). "Interestingly, the total population of CD4+ T cells had the highest induction activity, suggesting that other CD4+ non‐Treg cells in the TDLNs may indirectly participate the induction of Il‐17rb in cancer cells." (PMID 28993429, 2017). "Here, we show that in the context of a number of cancers, naïve CD45RA+ CD4 T cells are induced to express high levels of FOXP3, and that FOXP3 expression correlates with inhibition of T cell proliferation." (PMID 28239749, 2017). "Analysis of a combination of CD4/CD8, CD25, CD127, and FoxP3 markers revealed a statistically significant increase in the frequencies of Tregs within both the CD4 and CD8 subsets of circulating lymphocytes in patients with CIN3 and stage IA cancer." (PMID 29075318, 2017). "High density of CD4+ and CD56+ lymphocyte infiltrates within p16INK4a-positive cancer nests tumors correlated with better outcome in patients (p=0.039, p=0.013)." (PMID 28515351, 2017). "In accordance with our results, earlier studies have discovered evidence of CD4+ and CD8+ T cells in cancer nests and the peri-tumoral stroma." (PMID 29190964, 2017). "First, this data provides evidence that PD-1 can be used serve as a marker for both cancer antigen reactive CD8 and CD4 T cells in hematologic malignancies." (PMID 28642819, 2017). "P16INK4a-positive primary tumors had cancer nests less infiltrated with adaptive immune effectors: CD8+ (p=0.032), CD4+ (p=0.016) T lymphocytes as well as GZB+ cells (indicating combined cytolytic power of innate and adaptive TILs) (p=0.007)." (PMID 28515351, 2017). "Dysfunctional CD4+ and CD8+ T cells have been defined in both cancer patients and experimental models." (PMID 29375559, 2017). "CD4+, CD8+, FOXP3+, CD68+, CD56+ and GZB+ cells were detected within cancer cell nests or the mesenchymal stroma." (PMID 28515351, 2017). "Next, we compared the expression frequencies of chemokine receptors on CD4+ and CD8+ lymphocytes in unaffected mucosa versus carcinoma tissue." (PMID 29020986, 2017). "The percentages of CCR2+ cells in both subsets of CD4+ and CD8+ T lymphocytes were significantly lower in carcinoma tissue as compared with unaffected mucosa." (PMID 29020986, 2017). "The percentage of Tregs among the CD4+ T cells and MDSCs among CD45+ leukocytes in GC tissue from cancer patients was median 12.7% (range 1.7–37.6%) and median 2.8% (range 0.6–13.6%), respectively." (PMID 26799288, 2016). "We furthermore investigated the potential dependence of CD4+ and CD8+ TILs density from combined cancer cell and TILs expression of PD-1 and PD-L1." (PMID 26625204, 2016). "In previous studies, CD3, CD4, CD45RO, CD8, Foxp3+T cells and Myeloid-derived suppressor cells (MDSCs) are the most common infiltrating immune cells tested in cancers." (PMID 27602763, 2016).
cancer (continued). "Reduction in the percentage of CD4+ T cells expressing PD-1, CD73, CD160, or LAG3 by LYC-54143 was observed in differentiated human Type 17 T cells using PBMCs from cancer patients as well as healthy donors." (PMID 28123897, 2016). "The CD4/CD8 ratio is a sensitive and stable marker of cell-mediated immunity in cancer patients while absolute CD4+ cell counts usually show greater volatility under different physiological conditions." (PMID 27029063, 2016). "In various human cancers, CD3+CD4+RORγ+ cells are present at higher frequencies in the TILs than in PBMCs, suggesting a role for these cells in antitumor immunity." (PMID 28123897, 2016). "Using the less stringent criteria in the age analysis to identify subsets with trends, cancer patients showed increases in T box expressed in T cells (Tbet+)CD8+ and eomesodermin (EOMES)+CD8+, as well as Tbet+CD4+ cells." (PMID 28936253, 2016). "Polysaccharides isolated from A. annua L. (Huang-Hua-Hao) increase CD4+ and CD8+ T cells and IFN-γ and IL-4 secretion in HCC bearing mice, and induce cancer cell apoptosis in HCC." (PMID 26828466, 2016). "It is worth mentioning, that AE37 is a multipepitope vaccine, capable of inducing both specific CD4+ and CD8+ T cells in vaccinated cancer patients." (PMID 27891225, 2016). "The mean number of CD4+ TILs and CD8+ TILs was significantly lower in tumors that developed non-classic differentiation (NDN > 0) compared with samples from cancers with a classic histological pattern (NDN = 0)." (PMID 26927070, 2016). "Comparable frequencies of CD4+ and CD8+ Treg were detected in both types of cancer, although a predominance of either CD4+ Treg or CD8+ Treg was observed in different specimens." (PMID 26824503, 2016). "It is upregulated in naive T cells, B cells, in CD4+CD25+Foxp3+ regulatory T cells, and in various human carcinomas, and suppresses immune responses by producing extracellular adenosine." (PMID 27471640, 2016). "Significant differences were found with reference to the percentage of CD4 + CD25 + FOXP3+ Treg lymphocytes in malignant and non-malignant tumors between individual groups of patients (Kruskal-Wallis test; p = 0.003)." (PMID 26077607, 2015). "Previous studies have shown that (i) PD-1 is overexpressed on CD4- and CD8- T cells in several persistent infections and cancers, and (ii) that this overexpression plays a key role in the exhausted phenotype of these cells." (PMID 26633181, 2015). "Generation of CD4+CD25+ regulatory T cells is known to play a major role in progression and modulation of the immune-escape mechanisms in cancers." (PMID 26462021, 2015). "Adjuvant therapy of the main cancer therapy: HET increased lymphocyte cell-surface antigens, CD3-positive cells, and CD3/CD4 double-positive cells in elderly patients." (PMID 26379550, 2015). "Whereas mature DC, M1 macrophages, Th1 CD4+ T cells, and cytotoxic CD8+ T cells tend to reduce cancer growth in the vast majority of cancers, M2 macrophages, myeloid-derived suppressor cells (MDSC), and neutrophils exert an opposite effect." (PMID 25741340, 2015). "This study indicate that CD4+ T cells have opposing roles in OSCC progression and outcomes, which provides new insights relevant for the development of effective cancer immunotherapeutic approaches." (PMID 26587366, 2015). "We expectedly observed that tendency of CD4+IFN-γ+ T cells, both in fraction and relative cell numbers were significantly increased in the early and middle cancer stages." (PMID 25968569, 2015). "Although the association of Stat3 with individual complexes of the ETC has been previous described in heart and cancer cells, here we show for the first time the presence of Stat3 in the ETC SCs in CD4 cells." (PMID 25974216, 2015). "We further characterized the dynamic distributions of CD4+ T cell subsets and CD8+ T cells in different organs with varied cancer developmental stages in these two mouse models." (PMID 25968569, 2015).